MUC4 (mucin 4, cell surface associated)
Diseases named in the same sentence as MUC4 in open-access papers (continued):
Sharing a sentence is not in itself a finding about the gene and the disease.
cancer (continued). "MUC4, a large membrane-anchored glycoprotein, is aberrantly expressed in various types of cancers and inflammatory diseases." (PMID 27287498, 2016). "We selected 6 genes (MUC4, MUC13, MUC20, BMP7, AKT3, and SMAD3) that were closely associated with the development and progression of cancer to validate the conclusions drawn from the gene expression profiling analysis." (PMID 26673820, 2016). "We found that MUC4 knockdown decreased the accumulated migration distance and the velocity of cancer cells." (PMID 26393880, 2015). "Since then, MUC4 has been found aberrantly expressed in multiple human cancers, including lung, breast, gall bladder, prostate, ovarian, biliary tract and pancreas." (PMID 26393880, 2015). "Understanding the regulation of early deregulated genes (such as MUC4) will open new avenues in developing tools to target early steps of this deadly cancer." (PMID 26682251, 2015). "A murine NI model was established by implanting cancer cells in the periphery of the sciatic nerve, which was used to assess the effect of MUC4 on NI in vivo." (PMID 26393880, 2015). "We also showed that three mucin genes (MUC1, MUC2 and MUC4) expression in cancer cell line was regulated by DNA methylation." (PMID 24714692, 2014). "We have also found that the methylation status, mRNA expression, and mucin core protein expression were well correlated with each other for MUC1, MUC2, and MUC4 in cancer cell lines." (PMID 24714692, 2014). "We have previously demonstrated that MUC4 enhances tumorigenicity and metastasis in pancreatic and ovarian cancer." (PMID 23408941, 2013). "For instance, previous studies of MSLN and MUC4 defined positive labeling as focal antibody reactivity in more than 1% of cancer cells, while the present study required at least 10% of cells for an IHC score of 1+." (PMID 22792233, 2012). "MUC4/8G7 showed a significantly higher rate of the positive expression (≥5% of carcinoma cells stained) in well differentiated types (pap+tub1: 70%, 38/54) than that in poorly differentiated types (por1+por2: 18%, 10/55) (P<0.0001) (arrows)." (PMID 23152882, 2012). "MUC4 is normally expressed in many epithelial tissues, including respiratory, colonic, and vaginal epithelia and is overexpressed in various carcinomas such as breast, lung, ovarian, pancreatic." (PMID 23101681, 2012). "MUC4 plays critical roles in physiological and pathological conditions and is aberrantly overexpressed in several cancers, including those of the pancreas, cervix, breast and lung." (PMID 21886786, 2011). "MAbs 2214, 2175 and 2382 also recognized MUC4 expressed in the cancer tissues by immunohistochemical analysis with the reactivity pattern similar to that observed with anti-TR Mab 8G7." (PMID 21886786, 2011). "By contrast, MUC4 can promote cell proliferation and antiapoptotic effects in cancer cells by interacting with HER2 on the cell surface, suggesting the potency of functional domains in the extracellular domain of MUC4." (PMID 21349170, 2011). "Few of these markers were used for the confirmation of an MUC4 enriched cancer stem cell population." (PMID 21521521, 2011). "For instance, mucins such as MUC1 and MUC4 present on cancer cells participate in signal transduction pathways that contribute to the invasive and metastatic activities of adenocarcinomas." (PMID 21283832, 2011). "Further, MUC4 plays diverse functional roles in cancer initiation and progression as evident from its involvement in oncogenic transformation, proliferation, inhibition of apoptosis, motility and invasion, and resistance to chemotherapy in human cancer cells." (PMID 21886786, 2011). "In this sense, MUC4 can contribute to cancer progression due to its ability to inhibit recognition of cancer cells by the immune system, promoting tumor progression, metastasis, and suppression of apoptosis." (PMID 22295219, 2011).
cancer (continued). "This suggests that the isolated colonies from MUC4 overexpressed cells behave like cancer stem cells which are capable of maintaining the self-renewal property." (PMID 21521521, 2011). "Carraway and colleagues have conclusively demonstrated that MUC4, another large molecular weight mucin, shields cancer cells from lysis by the lymphokine activated killer cells due to its anti-adhesive properties." (PMID 20089172, 2010). "The PanIN3 stage, previously named in situ carcinoma, is characterized by a strong expression of MUC4 and MUC1 and occurrence of MUC3." (PMID 24281201, 2010). "MUC4-negative cancer cell lines and those with low MUC4 expression (eg, A427) were highly methylated near the transcriptional start site, whereas MUC4-positive cell lines (eg, NCI-H292) had low methylation levels." (PMID 19127263, 2009). "To examine the methylation profiles of 92 CpG sites in the MUC4 promoter in the cancer cell lines, we performed a MassARRAY methylation analysis." (PMID 19127263, 2009). "In the 10 cancer cell lines, methylation of CpG sites 108–112 was inversely correlated with MUC4 gene expression, whereas methylation of sites 1–107 was almost unrelated to gene expression." (PMID 19127263, 2009). "To investigate the possible epigenetic regulation of MUC4 gene expression, we mapped the DNA methylation status of the MUC4 promoter region using 10 cancer cell lines derived from carcinomas of four different organs (breast, lung, pancreas and colon)." (PMID 19127263, 2009). "Our results suggest that DNA methylation in the 5′ flanking region play an important role in MUC4 gene expression in carcinomas of various organs." (PMID 19127263, 2009). "MUC4 expression has also been reported in a variety of carcinomas including ovarian, lung, pancreatic, gall bladder, and breast." (PMID 19761616, 2009). "Different studies have shown the functional role of MUC4 in tumorigenicity and metastasis property of cancer cells." (PMID 18781152, 2008). "MUC4, is a membrane-bound mucin and has a significant role in different cancers including pancreatic and breast cancers." (PMID 18781152, 2008). "MUC4 is one of the most widely studied membrane-bound mucins having a significant function in the pathogenesis of several cancers." (PMID 18781152, 2008). "The mucin MUC4 is a transmembrane mucin that frequently displays an altered expression in many cancers." (PMID 18665193, 2008). "The expression of maspin, EMMPRIN, VEGF, MUC-4, and E-cadherin was stronger in the intestinal component of MT carcinomas than in their diffuse counterpart (p < 0.05)." (PMID 18266006, 2008). "We have previously reported that the inhibition of MUC4 expression by antisense technique in the well-differentiated cancer cell line, CD18/HPAF, reduced tumorigenicity, and metastasis in vivo." (PMID 17595659, 2007). "Another study performed on rat Muc4/SMC also proves the involvement of MUC4 mucin in growth advantage to cancer cells." (PMID 17595659, 2007). "In conclusion, our results suggest that MUC4 promotes tumorigenicity and is directly involved in growth and survival of the cancer cells." (PMID 17595659, 2007). "Inhibition of MUC4 expression using antisense or short-interfering RNA (siRNA) oligonucleotides specific to MUC4 results in a decreased tumorigenicity and dissemination of cancer cells." (PMID 15494719, 2004). "Additionally, evidence showing an inverse correlation between MUC4 expression and survival outcomes further demonstrates that its overexpression negatively impacts cancer progression." (PMID 40655139, 2025). "Increased aberrant expression of MUC4 has been shown in multiple human cancers, with evidence that cancer cells may use mucins for cell proliferation, survival, and protection against immune defenses." (PMID 39996934, 2025).
cancer (continued). "Significantly down-regulated genes in cancer tissue, compared to normal tissue included PLA2G2A, MUC4, PCK1, TXNIP, and genes encoding the CCR7 ligands, CCL19 and CCL21, which are lymphoid chemokines involved in the chemotaxis of lymphoid cells such as leukocytes and dendritic cells." (PMID 38505585, 2024). "Additionally, investigations of membrane-bound mucin genes (MUC1, MUC3, MUC4, and MUC13), associated with altered O-linked glycosylation in various cancers, were investigated through the GEO database (GSE16581) and underwent qPCR." (PMID 38274327, 2024). "MUC4’s spatial blocking effect aids in the evasion of the immune system’s attack by cancer cells." (PMID 38933439, 2024). "Notably, some studies have demonstrated that on the cell surface, MUC4 can diminish the effectiveness of anti-cancer medications by inhibiting the identification of targeted cells." (PMID 38933439, 2024). "However, in some carcinomas such as salivary gland MEC, overexpression of MUC4 was associated with better prognosis." (PMID 38243319, 2024). "These variations in the expression of MUC4 isoforms suggest that MUC4 might have different roles in cells, representing different cancer stages." (PMID 36675796, 2023). "The findings are consistent with studies of various cancers, in which the loss of C1GALT1 and their specific chaperones, COSMC, contribute to increased truncation of O-glycans on several mucin proteins, including MUC4 and MUC16." (PMID 35207462, 2022). "In the context of cancer, Dectin-1 targeting using free ꞵglucans and ꞵglucan-coated gold nanoparticles carrying a MUC4-TF peptide induces strong humoral responses, demonstrated by the presence of high titres of specific antibodies and antigen-recognizing T cells." (PMID 35454762, 2022). "Transmembrane mucin MUC4 is differentially expressed in various cancers." (PMID 35255004, 2022). "Retinoid acid (RA), the active form of vitamin A, could induce differential gene expression through the DNA methylation of homeobox transcription factor A1 (HOXA1) and potential oncogene mucin 4 (MUC4) genes in two cancer breast lines." (PMID 33924016, 2021). "In cancer research, the relevance of MUC4 to clinical outcome may suggest the potential pathogenesis of disease and stimulate further researches." (PMID 34336844, 2021). "Moreover, we assessed the relevance between MUC4 and immune marker genes to clarify the mechanism of MUC4 in immune regulation in cancers." (PMID 34336844, 2021). "Alteration frequency of MUC4 across different cancer types in cBioPortal." (PMID 34336844, 2021). "Furthermore, MUC4 is also a potential target for cancer immunotherapy, owing to its aberrant glycosylation and the existence of several splice variants." (PMID 34887447, 2021). "In addition, we examined the potential effects of MUC4 on prognosis across different cancer types via the Kaplan–Meier plotter." (PMID 34336844, 2021). "In our study, we conducted a comprehensive and profound bioinformatics analysis of MUC4 expression and correlation with prognosis and immune infiltration in cancer patients through Oncomine, TIMER2.0, PrognoScan, Kaplan–Meier plotter, GEPIA2, UALCAN, TISIDB, cBioPortal, and CVCDAP." (PMID 34336844, 2021). "AFP binding to ErbB2 can also enhance MUC4 interactions with ErbB2, ErbB3, and neuregulin, increase the phosphorylation of the ErbB2 complex and result in enhancing cancer cell proliferation, migration, invasion and inhibition of apoptosis through activating ERK and AKT signaling pathways." (PMID 33718192, 2021). "The consequence revealed that the high- and low- METAscore groups exhibited distinct mutation characteristics and the genes with a high mutation frequency in TTN, MUC4, PIK3CA, and MUC16 which all correlated with EMT and critical cancer pathways including PI3K/AKT and JAK2/STAT3 in CESC." (PMID 34277697, 2021).
cancer (continued). "Moreover, IL-17RB transcriptionally up-regulates expression of MUC1 and MUC4 to enhance cancer stem-like properties and resistance to gemcitabine." (PMID 33082357, 2020). "Furthermore, MUC4‐targeted cancer therapies have been reported and many prospective immunotherapies have been considered." (PMID 32745356, 2020). "While mucins play an essential role in forming a protective barrier over various tissues under normal physiological conditions, abnormal MUC4 expression has been reported in certain types of carcinomas, including those of the lung, breast, pancreas, and stomach." (PMID 32701958, 2020). "Notably we identified mutations within Mucin 4 (Muc4), which are potentially impactful due to Muc4’s emerging roles in Her2-positive cancer and metastasis." (PMID 31332182, 2019). "This should open new avenues regarding MUC4 potential as a therapeutic target in cancer." (PMID 31723153, 2019). "The expression levels of TTP and MUC4 were variable in cancer cells." (PMID 31141941, 2019). "In the present manuscript we also observe that MUC4 gene is amplified in 13% of cancer cell lines." (PMID 30236127, 2018). "MUC4 alterations were explored in Cancer Cell Line Encyclopedia dataset using cBioPortal webtool." (PMID 30236127, 2018). "Understanding the MUC4 interactome may improve the evaluation of specific predictive markers and the selection of the MUC4 pathway inhibitors in controlling cancer progression." (PMID 27829225, 2017). "Therefore, evaluating the presence and the resultant functional significance of MUC4 genomic alterations in various histological and stage subsets is important to further understand the role of MUC4 in cancer." (PMID 28978023, 2017). "MUC4 is a well-characterized protein for its significance towards cancer biology." (PMID 28978023, 2017). "However, as with the broadly decreased methylation seen in mucins, MUC4 shows significantly decreased methylation in 34 cancer cohorts and increased methylation in 12 cohorts." (PMID 28978023, 2017). "MUC4 levels inversely correlate with the 5′-UTR DNA methylation level in various cancer cell lines." (PMID 27829225, 2017). "It is no surprise that MUC4 is overexpressed, associated with poor prognosis, and potentially serves as a biomarker for cancer." (PMID 28978023, 2017). "One possibility was that some of the variant genes (e.g., MUC4) were pro-oncogenes, cells harboring these CNC variations were in a “precancerous” stage, and accumulation of other mutations would result in transformation and development of malignant neoplasms." (PMID 29262625, 2017). "However, because of the technical restrictions in cloning and modifying the large cDNA of MUC4, direct experimental proof for the role of individual MUC4 extracellular domain in cancer development and progression has been difficult to obtain." (PMID 27287498, 2016). "In cancers, MUC4 and the oncogenic receptor ErbB2 interact physically via the EGF-like domains." (PMID 26682251, 2015). "Similarly to this previous study, the MUC4 gene was shown to be upregulated by hypomethylation in the pre-cancer tissues compared with that in the normal tissues in the present study." (PMID 25789025, 2015). "Thus direct or indirect inhibition of MUC4 mucin would be an effective strategy to suppress MUC4 mediated cancer cell invasion and metastasis to distant organs." (PMID 25686822, 2015). "To evaluate the malignant functions of MUC4/Y, we summarized the distribution of DEGs in a number of pathways markedly related to the malignance of cancer using Database for Annotation, Visualization, and Integrated Discovery (DAVID, LIB) software and KEGG annotations." (PMID 25367394, 2014).
cancer (continued). "Immunohistochemistry for MUC4 may be a useful adjunct to morphological assessment of difficult cases in distinguishing urothelial CIS/carcinoma from its benign mimics." (PMID 24671186, 2014). "MUC4 promotes cancer growth and metastasis in part through interaction with the HER2 oncoprotein." (PMID 24204560, 2013). "Furthermore, other genes, such as MUC4 and AFAP1L2, associated with different human cancers, resulted overexpressed in DHH-RHEBL1-positive patients." (PMID 24127550, 2013). "Moreover, abnormal MUC4 expression has been reported in various cancers, such as pancreatic adenocarcinomas and colon carcinomas, as well as in other lung and airway inflammatory diseases including cystic fibrosis and chronic obstructive pulmonary disease." (PMID 24204934, 2013). "Interestingly, their results showed an 42% expression rate in the stage I cancers (n = 19), which is in accordance with our data (MUC4/8G7: 42% and MUC4/1G8: 48%) in the present study examining stage I cancers (n = 104)." (PMID 23152882, 2012). "Moreover, since there is controversy regarding the prognostic significance of these anti-MUC4 MAbs, a literature review of MUC4 expression in various cancers was also performed." (PMID 23152882, 2012). "MUC4 plays important roles in the lubrication and protection of the surface epithelium, cell proliferation and differentiation, immune response, cell adhesion and cancer development." (PMID 22793500, 2012). "We have previously reported that MUC4 expression is a poor prognostic factor in various carcinomas." (PMID 23152882, 2012). "Aberrant MUC4 expression has been observed in a variety of types of carcinoma." (PMID 23101681, 2012). "The enriched cancer stem cell population in MUC4 overexpressed cells may be due to the increased expression of HER2 expression." (PMID 21521521, 2011). "Functional studies using the non-tandem repeat MAbs may probably provide a better understanding of MUC4 mediated mechanisms in cancer progression." (PMID 21886786, 2011). "MUC4 frequently displays an altered expression under the pathological conditions of many cancers." (PMID 21521521, 2011). "Hence it will be of interest to study the effect of anti-MUC4 antibodies in inducing apoptosis in cancer cells and augmenting their sensitivity to chemotherapeutic drugs." (PMID 21886786, 2011). "The stronger signal strength of Mab 2214 with the lower bands could be due to the abundance of an immature MUC4 protein in the cancer cells." (PMID 21886786, 2011). "Furthermore, the cancer stem cell marker CD133 was expressed along with MUC4 in the isolated circular colonies as analyzed by both confocal and western blot analysis." (PMID 21521521, 2011). "Previous studies from our laboratory have shown that inhibition of MUC4 expression using anti-sense or short-interfering RNA (siRNA) oligonucleotides specific to MUC4 results in a decreased tumorigenicity and dissemination of cancer cells." (PMID 21886786, 2011). "Other antibodies directed against the mucins MUC1, MUC2 and MUC4 should also be evaluated, since these proteins are heavily glycosylated, and altered glycosylation in cancer may influence the reactivity to such antibodies." (PMID 19236510, 2009). "However, expression of MUC4 in Caco2 cells, which are derived from cancer cells of the same organ, was related to the DNA methylation status." (PMID 19127263, 2009). "It has been shown that MUC4 expression correlates with cancer progression." (PMID 18781152, 2008). "The aberrant expression of MUC4 has been reported in different types of carcinomas." (PMID 18781152, 2008). "MUC-4 is a heterodimeric glycoprotein complex and expressed in several human epithelial carcinomas." (PMID 18266006, 2008). "Cancer cells overexpressing MUC4 might use this strategy to survive and establish themselves before angiogenesis takes place." (PMID 17595659, 2007). "An overexpression of MUC4 mucin has been reported in a variety of cancers." (PMID 17595659, 2007).